OR6Q1 (olfactory receptor family 6 subfamily Q member 1)
Description:
Odorant receptor.
Synonyms: OR11-226
Tractability: Antibody: UniProt places it where antibodies can reach, with medium confidence; UniProt predicts a signal peptide or a membrane-spanning region; its Gene Ontology location is reachable by antibodies, with medium confidence. PROTAC: ubiquitination databases record sites on it.
Gene: Protein-coding gene on chromosome 11 (58,030,953 to 58,031,906, forward strand). Ensembl gene ENSG00000279051.
Subcellular location: Cell membrane
Pathways (Reactome):
Sensory Perception: Expression and translocation of olfactory receptors
Gene Ontology:
Molecular function: olfactory receptor activity; G protein-coupled receptor activity
Biological process: detection of chemical stimulus involved in sensory perception of smell; G protein-coupled receptor signaling pathway
Cellular component: plasma membrane; membrane
Genetic constraint (gnomAD): Loss-of-function variants: 2 observed, 2.58 expected, observed/expected ratio (o/e) 0.78, 90% interval 0.3 to 1.81. That is too few expected variants to judge how well the gene tolerates losing a copy. Missense variants: 387 observed, 400.88 expected, observed/expected ratio (o/e) 0.97, 90% interval 0.89 to 1.05. Synonymous variants: 143 observed, 157.13 expected, observed/expected ratio (o/e) 0.91, 90% interval 0.79 to 1.05.
Homologues: Orthologues: chimpanzee OR6Q1 (97% identical), macaque OR6Q1 (95% identical), rabbit OR6Q1 (90% identical), dog OR6Q1 (89% identical). Paralogues in human: OR6B2 (47% identical), OR6B3 (47% identical), OR11L1 (46% identical), OR5A2 (45% identical), OR5P3 (45% identical), OR9I1 (45% identical), OR6P1 (45% identical), OR5A1 (44% identical), OR5B12 (44% identical), OR8J2 (44% identical), OR8J1 (44% identical), OR5M11 (44% identical), and 84 more.
Diseases named in the same sentence as OR6Q1 in open-access papers:
OR6Q1 is named in the same sentence as 2 diseases in open-access papers, as found by Europe PMC text mining. Sharing a sentence is not in itself a finding about the gene and the disease.
OR6Q1 shares sentences with these, for which no sentence is quoted: neurodegenerative disease (1 paper); Parkinson disease (1).